RHOA (ras homolog family member A)
Diseases named in the same sentence as RHOA in open-access papers (continued):
Sharing a sentence is not in itself a finding about the gene and the disease.
atrial fibrillation (4 papers, 2015 to 2023). A disorder characterized by an electrocardiographic finding of a supraventricular arrhythmia characterized by the replacement of consistent P waves by rapid oscillations or fibrillatory waves that vary in size, shape and timing and are accompanied by an irregular ventricular response. "Evidences for this relation have been found in animal models of chronic kidney disease, where increased susceptibility to atrial fibrillation correspond to Cxs altered expression (in particular Cx40 and Cx43) and is a consequence of Ang II signaling and RhoA/ROCK pathway." (PMID 34209494, 2021). "RhoA represents a major stress signaling pathway, which was previously found to become activated during the progression of atrial fibrillation." (PMID 26193369, 2015). "Consequently, our current observation suggests that inhibitors of RhoA have beneficial effects in atrial fibrillation by preserving the HSR." (PMID 26193369, 2015). "Moreover, we observed that the cardioprotective effects of small HSPB family members in atrial fibrillation were accompanied by the attenuation of the RhoA signaling." (PMID 26193369, 2015). "In atrial fibrillation, disease progression coincides with both the induction of RhoA activity and the lack of cardiac cells to mount an adequate HSR to address the atrial fibrillation-induced damage." (PMID 26193369, 2015).
autism spectrum disorder (4 papers, 2019 to 2025). A spectrum of developmental disorders that includes autism, and Asperger syndrome. "Although it is estimated that 16p11.2 microduplication is associated with decreased RhoA protein levels, organoids derived from patients with autism spectrum disorder who had 16p11.2 duplications showed RhoA activation and slightly increased KCTD13 expression." (PMID 37958606, 2023).
brain injury (4 papers, 2017 to 2025). Acute and chronic (see also brain INJURIES, CHRONIC) injuries to the brain, including the cerebral hemispheres, CEREBELLUM, and brain STEM. "In traumatic brain injury, activated RhoA is detected for months after injury." (PMID 37296606, 2023).
cerebral infarction (4 papers, 2019 to 2020). An ischemic condition of the brain, producing a persistent focal neurological deficit in the area of distribution of the cerebral arteries. "In a rat model of focal cerebral infarction, RhoA was activated and upregulated in the lesion area after cerebral infarction." (PMID 32724667, 2020). "RhoA is involved in the proinflammatory cascades and was reported to be activated in the brain areas with focal cerebral infarction." (PMID 32240450, 2020). "The RVG29-NPs-miR124 group exhibited significantly decreased expression of RhoA in the Area of cerebral infarction." (PMID 32400219, 2020). "dl‐3‐n‐butylphthalide has been reported to protect endothelial cells against oxidative injury, reduce cerebral edema, and maintain BBB integrity by inhibiting the protein expression of RhoA in cerebral cortex surrounding rats focal cerebral infarction." (PMID 31334611, 2019).
chronic lymphocytic leukemia (4 papers, 2016 to 2023). "Doxorubicin mediates resistance in chronic lymphocytic leukemia (CLL) by upregulating RhoA/RhoA kinase, Ras/ERK1-2, Akt, HIF-1α, and P-gp activities; simvastatin inhibits this effect, overcoming doxorubicin resistance." (PMID 34065757, 2021). "Furthermore, simvastatin-reversed doxorubicin mediates resistance in unmated chronic lymphocytic leukemia (CLL) cells via upregulating Ras/ERK1-2, RhoA/RhoA kinase, Akt, HIF-1, and P-gp activities." (PMID 37760764, 2023).
Cirrhosis (4 papers, 2014 to 2021). A chronic disorder of the liver in which liver tissue becomes scarred and is partially replaced by regenerative nodules and fibrotic tissue resulting in loss of liver function. "Our results showed a highly significant difference in expression of RhoA among cirrhosis and early-stage HCC patients." (PMID 34469466, 2021). "Activated HSCs, in addition to their role in fibrogenesis, are responsible for the increased vascular resistance obseved in the hepatic sinusoid in cirrhosis, and these actions are thought to be mediated through the RhoA/Rho-kinase pathway." (PMID 25174394, 2014). "RhoA signaling is involved in cirrhosis driven carcinogenesis via LPA pathway as key regulator." (PMID 34469466, 2021). "It has been shown, that Shh and Gli are increased in cirrhosis, as well as RhoA/Rho-kinase-pathway." (PMID 26412302, 2015). "Our suggested mRNA signature including CTNNB1, RhoA, SPINK1, IFITM3 and SERPIND1, alongside other platelets mRNA, can be utilized as biomarkers for comparison of hepatic cirrhosis and HCC." (PMID 34469466, 2021). "RhoA, CTNNB1 and SPINK1 showed a significant 3.3-, 3.2- and 3.18-folds upregulation, respectively, in HCC patients compared to cirrhosis patients while IFITM3 and SERPIND1 presented a 2.24-fold change." (PMID 34469466, 2021). "A univariate Cox regression analysis was applied to identify important prognostic factors of recurrence-free survival, which tested parameters including age, gender, HBsAg status, cirrhosis, tumor size, TNM stage and Pin1/RhoA/RhoC co-expressions." (PMID 31324164, 2019).
Clear Cell Renal Cell Carcinoma (4 papers, 2014 to 2023). "Up-regulation of RhoA/ROCK and Cav-1 expression is considered to be associated with the development and progression of clear cell renal cell carcinoma (ccRCC)." (PMID 26066055, 2015). "Collectively, our data provide evidence that reduction of RhoA signaling by Activin B together with persistent Rac1 activity is a prerequisite for inducing an invasive phenotype in clear cell renal cell carcinoma." (PMID 25343250, 2014).
escherichia coli infection (4 papers, 2017 to 2025). Infection with the organism Escherichia Coli. "Among these genes, RHOA took in 5 pathways that were pathogenic Escherichia coli infection, vascular smooth muscle contraction, focal adhesion, adherens junction, and mRNA surveillance pathway." (PMID 29226137, 2017). "This suggests that RHOA plays an important role in the pathogenesis of Escherichia coli, and the development of drugs targeting RHOA protein for the treatment of Escherichia coli infection is of great potential." (PMID 40057776, 2025).
fibrosarcoma (4 papers, 2016 to 2023). A malignant mesenchymal fibroblastic neoplasm affecting the soft tissue and bone. "To experimentally verify this finding, we made use of previously established MAT systems in the fibrosarcoma cell line HT1080-doxycycline inducible expression of constitutively active RhoA (icaRhoA) and Src inhibitor dasatinib (DAS) treatment." (PMID 32369931, 2020). "For example, cytoplasmic dynein interacts with the microtubule-terminally related protein EB1 to promote fibrosarcoma cell migration through the activation of RhoA." (PMID 31249807, 2019). "Compared with normal fibroblasts, fibrosarcoma cells exhibit lower TRPM7 (another TRPP channel) and RhoA activity and are less sensitive to fluid shear stress." (PMID 37864030, 2023). "For example, normal fibroblasts, but not fibrosarcoma cells, reverse the migration direction within the microchannels in response to fluid shear stress through TRPM7 and RhoA activities." (PMID 37864030, 2023).
focal segmental glomerulosclerosis (4 papers, 2019 to 2023). A renal disorder characterized by sclerotic lesions in the glomeruli. "Excessive activation of RhoA in podocytes leads to albuminuria and focal segmental glomerulosclerosis in humans." (PMID 35222021, 2022). "Activation of RhoA results in FPE, decreasing actin-associated protein, podocyte apoptosis, focal segmental glomerulosclerosis, and fibronectin induction." (PMID 30536192, 2019).
Hypercholesterolemia (4 papers, 2016 to 2022). An increased concentration of cholesterol in the blood. "Interaction analysis showed that ACTB formed the hub of the revealed network, being involved in many interactions with other accessory proteins (e.g., with upregulated CAP1, WDR1, GSN, RHOA, and ARPC1A), suggesting myocardial cytoskeleton rearrangement in response to hypercholesterolemia." (PMID 35806390, 2022). "RhoA might also regulate glucose homeostasis, as pharmacological inhibition of RhoA’s target, ROCK, using Fasudil prevented high-fat diet-induced hypercholesterolemia and glucose intolerance in mice." (PMID 31075957, 2019).
influenza (4 papers, 2011 to 2019). An acute viral infection of the respiratory tract, occurring in isolated cases, in epidemics, or in pandemics; it is caused by serologically different strains of viruses (influenzaviruses) designated A, B, and C, has a 3-day incubation period, and usually lasts for 3 to 10 days. "And it is well documented that influenza infection induces activation of the monomeric GTP binding protein RhoA, protein kinase C (PKC), and Ras/ Raf/MEK/ERK signaling cascade." (PMID 29059211, 2017). "These experiments suggest that HRas\Raf\MEK\ERK, PKC-α, and RhoA are critical for influenza-induced ERK and MLC phosphorylation." (PMID 21731751, 2011). "Our studies indicate that inhibition of HRas\Raf\MEK\ERK, PKC-α, or RhoA is sufficient to suppress influenza-induced MLC phosphorylation." (PMID 21731751, 2011). "Findings of this study provide evidence that modulation of RhoA, Rabs and LC3 may be the underlying mechanisms for the inhibitory effects of simvastatin as an anti-influenza compound." (PMID 24788303, 2014). "However, in the present study, we showed that activation of HRas, PKC-α, and RhoA are required for influenza-induced ERK phosphorylation." (PMID 21731751, 2011). "Thus, the factors that restrict actin contractile function through inhibition of RhoA isoprenylation may have anti-influenza beneficial effects." (PMID 24788303, 2014). "In addition to ERK activation, influenza infection activates the signaling pathways upstream of MLC phosphorylation-PKC and RhoA/Rho kinase." (PMID 21731751, 2011). "Inhibiting MLC phosphorylation by blocking RhoA/Rho kinase, phospholipase C/protein kinase C, and HRas/Raf/MEK/ERK pathways with the use of genetic or chemical manipulation leads to the inhibition of influenza proliferation." (PMID 21731751, 2011). "Quercetin-3-O-α-L-rhamnopyranoside from RM was significantly effective against influenza infection by immunomodulatory properties, affecting the apoptosis pathway and binding ability to viral receptors M2 transmembrane and Neuraminidase of 2009 pandemic H1N1 and human RhoA cellular protein." (PMID 31791311, 2019).
lupus nephritis (4 papers, 2021 to 2024). Glomerulonephritis in the context of systemic lupus erythematosus. "Genetic knockdown of RhoA further was observed to suppress the apoptosis of renal tubular epithelial cells in mice with lupus nephritis." (PMID 38243295, 2024). "RhoA promoted the vitality of rat renal tubular epithelial cells (RTEC) in lupus nephritis (LN) mice and inhibited RTEC cell apoptosis." (PMID 33763149, 2021).
medulloblastoma (4 papers, 2014 to 2022). A malignant, invasive embryonal neoplasm arising from the cerebellum. "While it remains to be determined, it is possible that in medulloblastoma cells as well, loss of Na,K-ATPase function could modulate RhoA or Rac1 activity to inhibit EGF-induced motility and stress fiber formation." (PMID 25052069, 2014). "Similarly, FHOD3 promotes the occurrence of medulloblastoma by regulating RhoA/ROCK1/LIMK1 signaling." (PMID 34486491, 2021). "Also, Erk phosphorylation may be modulated by the counter‐balancing effects of Rac1 and RhoA activity levels in medulloblastoma." (PMID 36377725, 2022).
metastatic disease (4 papers, 2016 to 2024). "The first subtype encompasses mutations that consistently present in both primary gastric lesions and metastatic tumors, such as RHOA (6 mutations in primary gastric lesions/6 mutations in metastasis tumors) and TAF1L (1/1)." (PMID 38704377, 2024). "Thus, RhoA mediates genomic stability and represents a potential target for sensitizing metastatic tumors to genotoxic agents." (PMID 26823948, 2016).
pancreatic ductal adenocarcinoma (4 papers, 1998 to 2023). An infiltrating adenocarcinoma that arises from the epithelial cells of the pancreas. "To investigate the biological relevance of the rho genes in pancreatic carcinogenesis, we examined expressions of the rhoA, B and C genes by polymerase chain reaction after reverse transcription (RT-PCR) in 33 cases of ductal adenocarcinoma of the pancreas." (PMID 9459160, 1998).
rhabdomyosarcoma (4 papers, 2020 to 2025). A rare aggressive malignant mesenchymal neoplasm arising from skeletal muscle. "A published dataset investigating transcriptomic differences between five skeletal muscle and 101 rhabdomyosarcoma patient samples (GSE108022) found that VANGL2/RHOA, components of WNT signalling, were important in the regulation of growth and self-renewal of embryonal rhabdomyosarcoma (ERMS) cells." (PMID 35589804, 2022). "DEPDC1B was expressed in human Rh30 rhabdomyosarcoma cells, where DEPDC1B or RHOA knockdown promoted myogenic differentiation, but without influencing proliferation." (PMID 31825138, 2020).
uveal melanoma (4 papers, 2022 to 2023). A melanoma derived from melanocytes of the uveal tract. "Gαq/11 can also activate the Trio-RhoA pathway in C. elegans and in Gαq/11-constitutively active mutant uveal melanoma cells." (PMID 36055200, 2022). "For example, >80% of uveal melanomas and ~6% of cutaneous melanomas have mutations in GNAQ/GNA1 proteins, which stimulate RhoA activity and activate YAP/TAZ independent of any alterations in LATS1/272–74." (PMID 35768444, 2022).
viral myocarditis (4 papers, 2015 to 2024). Myocarditis that is caused by an infection with a viral agent. "ROCK2 mRNA has also been shown to be increased in viral myocarditis and suppressed by fasudil, an inhibitor of the RhoA/ROCK pathway." (PMID 38540212, 2024). "We determined whether SP mediated pathogenesis of viral-myocarditis is via NK1R-signaling and downstream RhoA activation." (PMID 25821814, 2015).
acute respiratory distress syndrome (3 papers, 2021 to 2025). Progressive and life-threatening pulmonary distress in the absence of an underlying pulmonary condition, usually following major trauma or surgery. "Die MS-Therapeutika Fingolimod und Siponimod sind in der Lage, das Recycling und die Expression von RhoA und RhoA/Aktin-abhängigen Makrophagenrezeptoren zu hemmen, und könnten somit potenziell ein ARDS („acute respiratory distress syndrome“) abschwächen." (PMID 33651117, 2021). "In addition, as RhoA/ROCK pathway activates Nf-κB, reduces eNOs activity, and increases ROS production, the upregulation of ROCK signaling might contribute to the induction of acute respiratory distress syndrome (ARDS) in COVID-19." (PMID 38666806, 2024).
adenoma (3 papers, 2015 to 2020). A neoplasm arising from the epithelium. "More detailed analysis showed that the expression of both GSK3A (0.01-fold with adjusted P < 1 × 10−6) and RHOA (0.35-fold with adjusted P < 0.01) in adenoma patients was significantly lower than those in normal healthy subjects." (PMID 31506480, 2019). "We found that RhoA-null adenomas maintained or upregulated pMLCSer19 signaling, suggesting likely compensation by RhoC or other related Rho GTPases." (PMID 26030593, 2015). "Fourth, we found an increase in the numbers of adenomas in the RhoAcKO sporadic lung tumor model in which RhoA is deleted by adenoviral expression of Cre." (PMID 26030593, 2015). "The interplay between RhoA and RhoC signaling is in some ways similar to that of B-Raf and c-Raf in oncogenic K-Ras-driven adenoma initiation." (PMID 26030593, 2015). "Rather, deletion of RhoA alone exacerbated lung adenoma formation, whereas dual deletion of RhoA and RhoC together significantly reduced K-RasG12D induced adenoma formation." (PMID 26030593, 2015). "Given that most adenomas evaded RhoA-deletion by CCSP-Cre, our results imply that there is selection pressure for the maintenance of RhoA signaling during KRasG12D-induced transformation." (PMID 26030593, 2015). "Immunohistochemical staining of the lungs of these mice demonstrated positive RhoA staining for all adenomas in the RhoWT group, whereas a fraction of adenomas stained positively in the RhoAcKO group." (PMID 26030593, 2015). "Although only ~15% of the adenomas observed were RhoA-null in the RhoAcKO group, we found numerous RhoA-null hyperplastic growths, including AAH." (PMID 26030593, 2015). "Fifth, an attempt at combined deletion of RhoA and RhoC resulted in reduced adenoma formation and retention of RhoA in all adenomas." (PMID 26030593, 2015). "Taken together, these results indicate that while RhoA and RhoC are each dispensable for K-RasG12D mediated tumorigenesis, together they contribute to adenoma formation." (PMID 26030593, 2015). "Due to the heterogeneity of RhoA-positive and RhoA-null adenomas in the RhoAcKO mouse group, we subdivided tumors based on their RhoA deletion status in our analysis." (PMID 26030593, 2015). "Moreover, when inactivation of RhoA signaling by transducing dominant-negative form of RhoA resulted in larger adenomas and decreased survival in a zebrafish model of KRAS-induced hepatic adenoma by rising AKT/S6 signaling and cyclin D1." (PMID 32244355, 2020). "In particular, every adenoma found in the DKO group retained RhoA and escaped recombination of the RhoAflox/flox allele whereas a portion of the tumors in the RhoAcKO group was completely depleted of RhoA, similar to that of the CCSP-Cre model." (PMID 26030593, 2015). "While a RhoA deletion band is present by PCR, it may be derived from heterozygous RhoA lox recombination or non-adenoma tissue." (PMID 26030593, 2015). "Deletion of RhoA appears to induce a compensatory mechanism that exacerbates adenoma formation." (PMID 26030593, 2015). "The RhoA expression status of each adenoma was quantified by immunohistochemistry." (PMID 26030593, 2015). "Therefore, similar to the CCSP-Cre model, RhoA-null adenomas were able to form by Adeno-Cre induction in K-RasG12D;RhoAflox/flox mice, indicating RhoA alone is not essential for K-RasG12D mediated tumorigenesis." (PMID 26030593, 2015). "We further assessed whether double deletion of RhoA and RhoC would affect K-RasG12D induced adenoma formation." (PMID 26030593, 2015). "We found that all adenomas in the RhoWT, RhoC-/- and DKO groups expressed RhoA in the Adeno-Cre induction model." (PMID 26030593, 2015). "Immunohistochemical staining revealed positive RhoA staining in all adenomas from the RhoWT, RhoC-/- and DKO groups, whereas only a subset of adenomas from the RhoAcKO group expressed RhoA." (PMID 26030593, 2015).
adenoma (continued). "Similar to the CCSP-Cre model, increased hyperplasia did not translate to differences in Ki67 or cleaved-caspase 3 staining of adenomas regardless of RhoA status." (PMID 26030593, 2015). "Additionally, immunohistochemistry for RhoA showed that almost all adenomas in the RhoC-/- and DKO stained positively for RhoA." (PMID 26030593, 2015). "Second, our data shows K-RasG12D-induced adenomas can form in the absence of RhoA, indicating that RhoA is not required for K-RasG12D-induced tumorigenesis." (PMID 26030593, 2015). "Our findings differ in that we do find RhoA-null adenomas, thus demonstrating that RhoA signaling is not essential for oncogenic K-Ras-induced adenoma formation." (PMID 26030593, 2015). "Interestingly, analysis of the RhoA status of the larger adenomas within the RhoAcKO group revealed that the relatively larger adenomas (>10,000 μm2) were ones in which RhoA was not fully deleted." (PMID 26030593, 2015). "Consistent with this interpretation, the phosphorylation status of MLC, downstream of RhoA and RhoC signaling, was not decreased in either RhoA or RhoC-null adenomas, nor in adenomas from DKO mice, in which RhoA is retained." (PMID 26030593, 2015).